SMAD4 (SMAD family member 4)
Diseases named in the same sentence as SMAD4 in open-access papers (continued):
Sharing a sentence is not in itself a finding about the gene and the disease.
colorectal cancer (continued). "Inactivation of SMAD4 by mutation or deletion is well described as an important and common event in the development of pancreatic and colorectal carcinoma, and less frequently is observed in cancers of numerous other localizations, including urinary bladder." (PMID 31238579, 2019). "Losses in 18q21.2, 5q21.1, and 17p12 loci were associated with reduced protein levels of three important colorectal cancer drivers: SMAD4; APC; and MAP2K4, respectively (FDR < 0.1)." (PMID 28854368, 2017). "Somatic mutations of SMAD4 are less common than loss of heterozygocity and are present in 2.1–20.0% of colorectal cancers." (PMID 28267766, 2017). "Sporadic mutations of SMAD4 are present in 2.1–20.0% of colorectal cancers (CRCs) but data are limited." (PMID 28267766, 2017). "Several studies support this notion: TGFBR1 mutations increase the overall risk of colorectal cancer and loss of SMAD4 in colon cancer results in worse survival and earlier recurrence." (PMID 27270652, 2017). "Subgroup analyses by cancer type showed that loss of Smad4 staining was associated with a worse outcome in colorectal cancer (HR = 2.54, 95% CI: 1.46–4.39; Pheterogeneity<0.001)." (PMID 25333693, 2014). "They further illustrated that there was a direct association between LIMK and BMPR2, and Smad4-independent BMP signaling activated the Rho/ROCK/LIMK pathway in colorectal cancer cells." (PMID 25501832, 2014). "In particular, although Smad4 is mutated in only of colorectal cancers, its mutation in concert with the others in the classical colorectal carcinogenesis model generates more aggressive tumor cells." (PMID 23922675, 2013). "The age-related changes would support an interpretation allowing for an enhanced risk in early life (most likely consequent on SMAD4 and polyposis predispositions), but possible protection from other forms of colorectal cancer later in life." (PMID 24354965, 2013). "It had been expected that rates of colorectal cancer would be higher in HHT because of the population subgroup with SMAD4 mutations and juvenile polyposis." (PMID 24354965, 2013). "Loss of 18q is a common event in colorectal cancer, and 18q deletion and loss of SMAD4 expression are associated with liver metastasis." (PMID 23158542, 2012). "Inactivation of BMPR1A, BMPR2, and SMAD4 was frequently observed in sporadic colorectal cancer, correlating to loss of Smad1/5/8 phosphorylation." (PMID 22072987, 2011). "In cancer cells, a panel of 4 missense mutations in the MH1 domain of Smad4 identified in human pancreatic and colorectal cancers was reported to render the mutant Smad4 a better substrate for poly-ubiquitin modification and proteasome-mediated degradation." (PMID 22204598, 2011). "Loss of expression and allelic imbalance at the SMAD4 locus has been shown to promote carcinogenesis of gastric, ovarian, and colorectal cancers." (PMID 21835029, 2011). "To this end we used pairs of cell clones derived from the human Smad4-deficient colorectal cancer cell lines SW480 and SW620, in which Smad4 expression was stably restored." (PMID 20307265, 2010). "In contrast, Smad4 mutation and its reduced level in colorectal cancer are directly correlated to poor prognosis and increased metastasis." (PMID 18781153, 2008). "Smad4 mutation and its reduced level in colorectal cancer are directly correlated to poor prognosis and increased metastasis, whereas Smad7 expression is associated with poor outcome in gastric carcinomas." (PMID 18781153, 2008).
colorectal cancer (continued). "In contrast, mutation or reduced level of Smad4 in colorectal cancer is directly correlated to poor survival and increased metastasis." (PMID 18781153, 2008). "A subset of colorectal cancers has been shown to have mutations or down-regulation of the type 1 receptor, type 2 receptor, Smad2 and Smad4." (PMID 17692120, 2007). "Smad4 protein expression level and allelic loss at 18q21 are associated with the process of liver metastasis in colorectal cancers evaluated when excluding clinical and pathological features except for liver metastasis." (PMID 17088901, 2006). "It has been reported that inactivation of the Smad4 gene and allelic loss of chromosome 18q correlate with liver metastasis and poorer prognosis in colorectal cancers." (PMID 17088901, 2006). "We, too, recently discussed the association between Smad4 level and prognosis in colorectal cancers." (PMID 17088901, 2006). "In conclusion, our results showed that both chromosome 18q deletion and Smad4 protein expression are associated with liver metastasis in colorectal cancers, and that they both play an important role in the development of liver metastasis." (PMID 17088901, 2006). "Subsequently, Smad4 gene was detected as another target at 18q21.1, whose mutations were detected up to 35% of colorectal cancers." (PMID 17088901, 2006). "In conclusion, our findings indicate that Smad4 point mutations are infrequent in early stages of colorectal cancer." (PMID 12569386, 2003). "Owing to the significance of LOH in colorectal cancer and the role of the remaining gene, this study was focused on patients with an allelic loss of one Smad4." (PMID 12569386, 2003). "Our screen of 73 patients with early-stage colorectal cancer (I–III) carrying a loss of one Smad4 allele identified two mutations of the remaining allele (3%), a finding that is in accordance with results described in the literature." (PMID 12569386, 2003). "The aim of the present study was to determine the clinical alterations and the significance of its mutations in a series of colorectal cancers previously examined for SMAD-4/DPC-4 gene." (PMID 9820171, 1998). "Hereditary polyposis syndromes (HPS) including familial adenomatous polyposis (FAP), juvenile polyposis syndrome (JPS), and Peutz-Jeghers syndrome (PJS) are all predisposing conditions to colorectal cancer, with a genetic basis (mutations in SMAD4 or BMPR1A genes)." (PMID 41258467, 2025). "As well as extensive circumstantial data associating high SPP1 expression in human colorectal cancer, Spp1 was also previously reported to be a key Smad4 dependent expressed gene functionally associated with murine prostatic cancer invasion in a Pten prostate deletion model." (PMID 40348815, 2025). "Additionally, high Smad4 expression was associated with prolonged survival in patients with colorectal cancer." (PMID 39664586, 2024). "The correlation of SMAD4 loss with a worse course of colorectal cancer development may be due to the promotion of chemoresistance to 5-FU in these patients." (PMID 37237640, 2023). "In addition, mutational status of SMAD4 had a role in predicting prognosis after resection of liver metastases from colorectal cancer." (PMID 37685308, 2023). "Patients with colorectal cancer harboring SMAD4 pathogenic variants may obtain more benefit from adjuvant chemotherapies that do not include irinotecan." (PMID 35685436, 2022). "Loss of tumor suppressor SMAD4 occurs in about 30% of colorectal cancer (CRC) cases." (PMID 35034624, 2022). "Sporadic SMAD4 mutation is found in approximately 10–20% of colorectal cancers." (PMID 35892903, 2022). "The aim of this study was to investigate the relative abundance of the transcript SMAD4–201 in colorectal cell lines and tissues in order to establish if its fluctuations may be associated with colorectal cancer (CRC)." (PMID 35034624, 2022).
colorectal cancer (continued). "Indeed, activation of the WNT/β-catenin pathway is required even in the presence of SMAD4 inactivation in BRAF-associated colorectal cancers." (PMID 36079062, 2022). "In addition, SMAD4 loss in colorectal cancer has been associated with higher tumor and nodal stage, shorter relapse-free survival in 5-FU-based chemotherapy, and less immune infiltration in the tumor microenvironment." (PMID 35892903, 2022). "Search for SMAD4 mutations in Colorectal cancer (CRC) or polyp in Iran." (PMID 35154600, 2021). "SMAD4 mutations were reported in 2.1–31% of colorectal cancer cases." (PMID 35154600, 2021). "Wasserman and the colleagues demonstrated that Smad4 is closely associated with the high risk of recurrence or death of colorectal cancer patients, and the loss of Smad4 predicts worse clinical outcome, decreased immune infiltrate, and resistance to chemotherapy." (PMID 31721429, 2020). "Early colorectal carcinoma was found to be associated with Smad2 and Smad4 inactivating mutations." (PMID 32508821, 2020). "Considering its high occurrence in colorectal cancer, these variants may reduce activity of SMAD4 and contribute to the development of colorectal cancer." (PMID 30709382, 2019). "SMAD4 is one of the most mutated genes in colorectal cancer." (PMID 30709382, 2019). "Previous studies have shown that loss of SMAD4 is found in 30–40% colorectal cancer patients, which occurs late in adenoma-to-carcinoma sequence, leading to liver metastases, and these patients have a poor response to chemotherapy following with poor prognosis." (PMID 30745456, 2019). "In colorectal cancer, aside from loss of Smad4, TβRI and TβRII are commonly downregulated or lost." (PMID 27829391, 2016). "Mutations of the Smad4 gene in other tumor types are less frequent, with a 16% rate in biliary tract cancers, 13% in colorectal carcinomas, 12% in breast cancers, bladder cancers and ovarian cancers, 7% in lung cancers, 6% in hepatocellular carcinoma and 4% in cervical cancers." (PMID 24047375, 2013). "The human 5q22.2 and 18q21.1-q21.2 regions are both constantly disrupted in human CRCs, and encode bona fide CRC driver genes (e.g., APC, SMAD4) as well as genes whose role in cancer etiology remains unclear (e.g., mutated in colorectal cancer or MCC)." (PMID 20707908, 2010). "Our study was carried out to clarify the involvement of SMAD4 in the development and progression of colorectal carcinoma where it is reported to be mutated or deleted in about 20% of invasive cases and the relationship between the mutant status of SMAD4 and KRAS genes." (PMID 20565773, 2010). "Mutations in SMAD2 or SMAD4 occur frequently in pancreatic and colorectal carcinomas." (PMID 20573232, 2010). "Allelic loss at 18q21.1 and mutations of SMAD4 are common alterations in colorectal cancer." (PMID 17407575, 2007). "Somatic SMAD4 mutations have been detected in some colorectal carcinomas." (PMID 10993648, 2000). "Lastly, although we were able to identify recurrent CNA events in our mouse colorectal carcinoma model, roughly a third (nine of 28) of the tumors (despite having ≥30% tumor content) had no detectable aneuploidy or prioritized mutations/focal CN events or Smad4 loss." (PMID 41051921, 2025).
colorectal cancer (continued). "However, mutations of SMAD4 occur only in a minority of BRAF mutated colorectal cancers and accumulation of alternative lesions may be needed to advance BRAF-associated carcinogenesis." (PMID 36079062, 2022). "Indeed, mutations leading to loss of function of SMAD4 have been reported in juvenile polyposis syndrome, characterized by the presence of polyps in the digestive tract in children and an increased rate of colorectal cancer." (PMID 35907855, 2022). "SMAD4 mutations have recently been reported in 5–20% sporadic colorectal carcinomas (CRC) where they were associated with distant metastases and/or poor prognosis in some studies but not others." (PMID 30730996, 2019). "When colorectal cancer was analyzed, age (OR = 1.69, 95% CI: 1.09–2.61; Pheterogeneity = 0.648) and stage (OR = 2.31, 95% CI: 1.71–3.10; Pheterogeneity = 0.218) but not gender (OR = 0.85, 95% CI: 0.30–2.44; Pheterogeneity = 0.013) were positively associated with loss of Smad4 staining." (PMID 25333693, 2014). "While statins show moderate promise for colorectal cancer (CRC) chemoprevention, especially in subtypes characterized by SMAD4 positivity, APC mutations, or KRAS-driven pathways, the evidence is not yet sufficient to recommend their clinical use." (PMID 41170235, 2025). "Hence, we hypothesized that in addition to aneuploidy-based loss of Smad2, Smad4, and Dcc in these five colorectal carcinoma tumors, as all our colorectal carcinoma tumors had two copy loss of the floxed Apc allele, the somatic APC copy loss event may also have affected the three known TSGs." (PMID 41051921, 2025). "Furthermore, focal Smad4 single copy loss occurred more often than expected compared with the loss of other oncogenes, TSGs, and cancer-related genes (Z-proportion test: P value = 2.2e−5), supporting the fidelity of Smad4 loss in our colorectal carcinoma mouse models." (PMID 41051921, 2025). "SMAD4 has a distinctive role in the initiation and progression of colorectal cancer, but its transcriptional regulation remains understudied 2, 5, 34-36." (PMID 39132157, 2024). "Loss of SMAD4 is a hallmark of PDAC and other gastrointestinal tumor types, like colorectal cancer (CRC), and has been linked to AGR2 up-regulation." (PMID 39727484, 2024). "RAS, BRAF, and SMAD4 are negatively associated with OS and RFS in patients undergoing curative liver metastasectomy from colorectal cancer." (PMID 39220128, 2024). "Most recently, pan-omics analysis on commercially available colorectal cancer organoids revealed the role of SMAD4 inactivation in pro-migratory, cell proliferation and tumorigenesis." (PMID 38461268, 2024). "Black raspberry enhances the expression of the transcriptional effector Smad4 in colonic epithelial cells and natural killer cells, thereby inhibiting colorectal cancer." (PMID 39100676, 2024). "SMAD4 is a crucial transcription factor in TGFβ signaling and functions as a tumor suppressor in colorectal cancer." (PMID 39100676, 2024).
colorectal cancer (continued). "In order to further investigate the expression of Smad4 in mouse colorectal cancer, two distinct mouse CRC models were developed." (PMID 39439794, 2024). "This study showed that SMAD3, SMAD4, and their proteins were significantly underexpressed in colorectal cancer." (PMID 36969909, 2023). "In colorectal cancer, SMAD4 gene expression is involved in inducing resistance to 5-FU-based therapy." (PMID 37237640, 2023). "A growing body of evidence confirms that SMAD4 is lost in colorectal cancer at a frequency of approximately 30%." (PMID 37685308, 2023). "The present study evaluated changes in the expression of the SMAD4 gene in advanced colorectal cancer cell lines under the influence of various concentrations of 5-FU." (PMID 37237640, 2023). "Colorectal cancer can occur in carriers of either BMPR1a or SMAD4 DCVs but is less common in carriers of BMPR1a DCVs than SMAD4 DCVs, and upper GI malignancy in carriers of BMPR1a DCVs does not appear to occur." (PMID 37400896, 2023). "The application of lantern-shaped flexible RNA origami in the context of the tumor suppressor gene, Smad4 in colorectal cancer models demonstrates promising potential for accurate manipulation of protein levels in in vitro and in vivo settings." (PMID 36894556, 2023). "As high SMAD4 expression is a desirable predictor in patients with colorectal cancer, especially in advanced stages, determining SMAD4 expression before treatment can be used to estimate the potential benefits of the planned therapy." (PMID 37237640, 2023). "For example, USP3 depletion promotes the development of colorectal cancer through decreasing SMAD4 expression." (PMID 37980532, 2023). "We showed that after the delivery of Smad4 mRNA, the downstream oncogenes can be transcriptional regulated effectively, and significant suppression of colorectal cancer growth was observed both in vitro and in vivo." (PMID 36894556, 2023). "In particular, Tang and colleagues pointed out that SPTBN1/Smad4/TGF β signaling acts as a suppressor of colorectal cancer progression." (PMID 38069214, 2023). "Taken together, these results show that SMAD4 restoration through efficient transposon transfection restores TGFβ-induced growth inhibition in colorectal cancer cells, in vitro and in vivo." (PMID 37377893, 2023). "Colorectal cancer occurs at a similar incidence in both causative genes of JPS, where 15/127 (11.8%) had CRC in SMAD4 carriers, compared to 7/94 (7.4%) in BMPR1A carriers." (PMID 38066625, 2023). "Here, the authors develop a lantern-shaped flexible origami for nanolization of single mRNA molecules and demonstrate efficient delivery of Smad4 mRNA, achieving suppression of colorectal cancer tumour growth." (PMID 36894556, 2023). "A SMAD4‐modulated gene expression profile identified high‐risk stage II and III colorectal cancer patients, can predict disease‐free survival, and has prognostic potential for stage II and III colorectal cancer patients." (PMID 34114372, 2022). "miR-20a-5p was recently identified as a cancer promoter, which can promote triple-negative breast cancer cells growth via targeting RUNX3 and promote colorectal cancer invasion by downregulating Smad4." (PMID 35351042, 2022). "Variations of SMAD4 copy number also has implications of predicting response to 5-FU therapy in colorectal cancer." (PMID 35565354, 2022).